TNF (tumor necrosis factor)
Diseases named in the same sentence as TNF in open-access papers (continued):
Sharing a sentence is not in itself a finding about the gene and the disease.
cancer (continued). "In cancer cachexia, lipolysis is activated by various factors, including enhanced stimulation of β-adrenergic receptors; increased secretion of cytokines, such as TNF-α, IL-1, IL-6, and interferon-γ; and increased expression of lipid-mobilizing factors, such as zinc-α2 glycoprotein-1 (AZGP1)." (PMID 30754663, 2019). "Also, patients treated with anti-TNF agents may need to undergo a more intensive degree of cancer surveillance program to detect dysplasia and cancer." (PMID 31048714, 2019). "Therefore, the modulation of TNF-α-mediated survival signals may result in the sensitization of cancer cells to the TNF-α-induced apoptosis." (PMID 31766230, 2019). "Therefore, the inhibition of TNF-α-induced NF-κB and AP-1 activity has been considered in the search for drugs that could effectively treat cancer." (PMID 31766230, 2019). "Interestingly, a subset of identified cancer biomarkers (TNFα, sFasL, TRAIL, prolactin, FGF2, SCF, OPN), which were identified in the high diversity/inflammation cluster, were also correlated with Lactobacillus abundance, vaginal pH and genital inflammation and were elevated in the ICC group." (PMID 31089160, 2019). "Our analysis of TNFα up-regulated genes, compared to data from 519 HNSCC samples obtained from TCGA, identified several genes that correlated with decreased disease-free survival (DFS) and decreased overall survival (OS) some of which have been previously associated with cancer progression." (PMID 30018735, 2018). "For instance, IL-34 stimulates intestinal immune cells to make TNF-α and IL-6, two cytokines exerting proliferative effects on CRC cells, and has been involved in the suppressive function of regulatory T cells, a subset of T cells whose activity associates with the progression of cancer cells." (PMID 29423057, 2018). "Eighteen monotherapy phase I and 10 phase II clinical trials were performed using recombinant human TNF (hTNF) therapy as anti-cancer agent, but none of them was successful as systemic TNF treatment was found to cause dose-dependent toxicities such as fever, hypotension and tachycardia." (PMID 29751683, 2018). "Furthermore, the increased IL-10 and TNF-α levels lead to a decrease in the lymphocyte count, a crucial component of innate immunity and the adaptive immune response, with a relevant role in the immune surveillance process towards cancer cells." (PMID 29983708, 2018). "Furthermore, our analysis reveals that toxin may affect IL6-expression via a number of mechanisms, including JAK-STAT cascade, cytosolic DNA-sensing, TNF signaling pathway and transcriptional misregulation in cancer cells." (PMID 29593668, 2018). "Interestingly, reports have shown the existence of cross talk between the TNFα‐NFkB signaling pathway and the coactivator Gadd45β, and strong staining of GADD45β has also been detected in multiple human cancer tissues." (PMID 29706024, 2018). "Since cytokines play a central role in the cross-talk among immune cells during chronic inflammation, some authors have suggested that modification in the circulating level of several cytokines, particularly TNFα, IL-6, and IL-10, may contribute to cancer promotion and progression." (PMID 30583555, 2018). "Therefore, we hypothesized that KLT may suppress the invasion and migration induced by TNF-α in cancer cells." (PMID 29467927, 2018). "Therefore, the possible common mechanism by which obesity induces inflammation in several cancers (pancreatic, lymphoma and glioblastoma) might be through TNF-α-induced NF-κB signaling." (PMID 30567565, 2018). "Also unknown is the impact of the combination of immunosuppression with steroids and infliximab on overall survival and the risks of these agents in immunocompromised patients with active cancer who begin potential long-term use of anti-TNFα therapy." (PMID 30518410, 2018).
cancer (continued). "NK cell function is significantly downregulated following exposure to cancer cells in humans and mice, as demonstrated by lower expression of activating surface receptors, decreased cytotoxic granule release and cytotoxicity, and reduced secretion of TNF-α and IFN-γ." (PMID 29977235, 2018). "Moreover, the cytokines involved in cancer-related inflammation, IL-6 and TNFα, may induce neutrophilia." (PMID 29890986, 2018). "Moreover, GSK-J4 reduced IFN-γ, TNFα, granulocyte–macrophage colony-stimulating factor (GM-CSF), and interleukin-10 levels in cytokine-stimulated NK cells while sparing their cytotoxic killing activity against cancer cells." (PMID 29301935, 2018). "Thus, future studies should evaluate whether TNF-α triggered IL-6 secretion in VSMC is achieved through similar mechanisms described for cancer cells and macrophages." (PMID 29750813, 2018). "Therefore, it is desirable to estimate what effects the molecular alterations have on TNF-α protein expression, because it could allow us to predict the grade of inflammatory response in cancer patients." (PMID 29802455, 2018). "Therefore, as is the case in cancer cells, a positive TNF-α autocrine/paracrine loop in response to LPS may lead to persistent NF-κB activation in myoblasts, further inhibiting myogenesis and thus inducing muscle wasting." (PMID 28742154, 2017). "However, TNFα can mediate the maturation of a granulocyte-macrophage lineage and may protect myelosuppressed cancer patients from bacterial infections by increasing bacteriocidal phagocytic cytotoxicity." (PMID 28793897, 2017). "Cancer therapy induces the production of reactive oxygen species that in turn incite an inflammatory response by activating nuclear factor kappa B and amplifying TNF-α, which results in the disruption of the epithelial cell barrier and translocation of colonizing bacteria." (PMID 28678827, 2017). "However, we did not observe a statistically significant association between TNF-1031 T/C rs1799964 and cancer (P=0.23)." (PMID 29118938, 2017). "Finding strategies to harness this ability of TNF-α and similar members of its superfamily towards enhanced cell death (e.g. in cancers) or cell survival (e.g. in neurodegenerative diseases) might provide an important tool for therapeutic interventions in human disease." (PMID 28323882, 2017). "Whether anti-TNF antibodies affect the anti-cancer immune response remains unknown." (PMID 29273790, 2017). "Because none with solid cancer or overall cancer used TNF-α inhibitors, we could not assess their association." (PMID 29287101, 2017). "TNF-α may be a key to improve anti-cancer effect of HDAC inhibitors." (PMID 28099148, 2017). "Furthermore, in our past study, we demonstrated that curcumin could inhibit EMT induced by TNFα, when it combined with antitumor vaccine which had significant effect on treatment of cancer." (PMID 29312546, 2017). "Furthermore, in the context of cancer immunotherapy TNF-α may serve as an adjuvant in order to enhance T-cell infiltration." (PMID 29276511, 2017). "The most relevant pro-inflammatory cytokines contributing to the development of cancer cachexia and related with the metabolic alterations leading to muscle mass and adipose tissue wasting are interleukin-1, interleukin-6 (IL-6), tumor necrosis factor alpha (TNF-α), and interferon gamma." (PMID 29376055, 2017). "The TNF-α serum level may have clinical significance in the development of cancer cachexia." (PMID 28489606, 2017). "However, although IL-6 did not change during cancer treatment, the symptom cluster was associated with both TNF-α and IL-6, suggesting that only part of the inflammation leading to symptom experience was due to treatment." (PMID 28616125, 2017). "Therefore, we supposed that TNF-α might widely influence the expression of oncogenes including HBXIP in cancers." (PMID 28938560, 2017).
cancer (continued). "Considering gene therapy, the control of transgenic expression, via resveratrol activation, of Egr-1 promoter may sensitize cancer cells, extending the use of Ad.Egr-TNF to patients intolerant of radiation or chemotherapy, offering a novel tool for development of inducible gene treatments." (PMID 27148534, 2016). "Mechanisms by which neutrophils and other CD11b+ cell types may kill cancer cells include TNF-α secretion/TRAIL mediated killing, Reactive Oxygen Species (ROS) including hydrogen peroxide (H2O2) and nitric oxide (NO), and possibly contact-dependent killing similar to that of NK cells." (PMID 27806313, 2016). "Collectively, CCR4 may play an important role in TNF-α-mediated cancer cells metastasis." (PMID 27356745, 2016). "This means TNF may have a role in the proliferation of cancer cells." (PMID 27821804, 2016). "Consequently, TNF-α seems to be having complicated roles in cancer." (PMID 26881177, 2016). "Finally, because TNF-α is known as a key mediator of muscle atrophy in cancer cachexia and crosstalk between the TNF-α and Notch pathways has been described in cancer development and metastasis, we also investigated the potential of TNF-α to mediate Notch activation in muscle cells." (PMID 27378829, 2016). "Hence, the ability of DpC to increase TNFα in tumors could promote the endogenous immune response to mediate immune cell infiltration of the cancer." (PMID 27678372, 2016). "In this study we demonstrated that TNF-α, which could represent a good maturation model in allogeneic response field, appeared as dramatically counter-productive in the induction of mature DCs for cancer therapy." (PMID 27080531, 2016). "Moreover, several GT genes were shown to be regulated at the transcriptional level by pro-inflammatory cytokines such as tumor necrosis factor (TNF) or interleukin 6 (IL-6), leading to the expression of sialylated structures such as sLex also observed in cancers." (PMID 27916834, 2016). "Moreover, the chemokine receptor CCR4 might be involved in TNF-α-induced expression of MMP13 in CRC cells, suggesting the drugs targeting CCR4 may provide a clue for antagonizing TNF-α-regulated cancer cells metastasis." (PMID 27356745, 2016). "Moreover, the D149G mutation on p21WAF1/CIP1 could attenuate Serine 146 phosphorylation by PKCδ to resist tumor necrosis factor α-induced apoptosis and play an important role in cancer development." (PMID 26930193, 2016). "In addition to epidermal renewal, IngMeb also activates Protein Kinase C -delta (PKC-δ) which has been found to induce apoptosis in cancer cell lines and induce upregulation of neutrophil mediators, (IL-8, TNF-α, ICAM-1, and E-selectin), resulting in massive neutrophil invasion to the skin." (PMID 27636884, 2016). "Also, osteopontin appears to act in a feed-back loop with cancer cells, stimulating their proliferation, as well as adipocytes, where osteopontin stimulates the synthesis of inflammatory cytokines such as IL-6 and TNFα." (PMID 27049717, 2016). "The potency of cytokines like TNFα and the CC chemokine family in fundamental immune functions such as control of infection, leads to real concerns about the cost to benefit relationship of positive effects on disease vs compromising the ability of the body to control infections and cancers." (PMID 26620767, 2015). "Indeed, several studies have demonstrated that microRNA-21 could be upregulated by TNFα in cancer or in some inflammatory pathology." (PMID 26714738, 2015). "Furthermore, TNF-α seems to be involved in the progression of cancer cachexia." (PMID 26508818, 2015). "Furthermore, a significant reduction of the endogenous NIBP expression in cancer cells by lentivirus-mediated NIBP shRNA inhibited TNFα-induced phosphorylation of IKK1/2 and p65, and degradation of IκBα at 5-30 min of TNFα treatment with most dramatic inhibition at 30 min." (PMID 25704885, 2015).
cancer (continued). "However, the regulation of signal transducer and activator of transcription-1 (STAT-3) was constitutively active and presented a slight down-regulation after the combination of IFN-γ and TNF-α treatment, which is consistent with others results in the cancer cells." (PMID 25811609, 2015). "This could be explained by the fact that TNFα exerts its potent cytotoxic effects on tumors in vivo via the death receptor-dependent apoptotic pathway, but also via its anti-angiogenic effects, believed to be critical for its anti-cancer activity." (PMID 25933695, 2015). "We continued to examine whether the Chinese medicine XAT might affect the activity of the proinflammatory cytokines IL-1β and TNF-α, which are important in the development of inflammation and cancer pain, as well as the anti-inflammatory cytokine IL-10, which may inhibit inflammation and pain." (PMID 26617438, 2015). "tRXRα-mediated activation of the TNFα/PI3K/AKT pathway significantly promotes cancer cell growth both in vitro and in vivo, providing a potential approach to inhibit cancer cell growth by targeting tRXRα with small molecules to inhibit TNFα/PI3K/AKT survival pathway." (PMID 26156677, 2015). "In response to unknown or foreign antigens whatever their origins (e.g., pathogens, cancers and/or vaccines), a number of cytokines are produced by the cellular component among which are interleukin (IL) 1, IL-6, tumor necrosis factor α (TNFα), and interferon γ (INFγ)." (PMID 25803545, 2015). "However, in this study they reported that long-term use of curcumin may attenuate cancer progression via the down-regulation of TNF-α and of IL-6 modulated by E26 transformation-specific protein (ETS) and NF-κB." (PMID 25665066, 2015). "The negative correlation also found between the plasma concentrations of IL-1β and numbers of CD4+NKG2D+ T cells in cancer patients may simply be an independent variable resulting from the fact that IL-1β is typically activated in situations where TNF-α is produced." (PMID 26486970, 2015). "We therefore further hypothesize that TD HER2 trogocytosis, which results in reduced target cancer cell HER2 expression, could induce target cancer cell death by pro-apoptotic proteins, such as granzymes and TNF-alpha, in addition to inducing trastuzumab-mediated ADCC." (PMID 25655677, 2015). "Hence, these agents may be useful for the treatment of some cancers (for prevention purposes only) where TNF is a distinct etiologic factor (e.g., inflammation)." (PMID 24664144, 2014). "However, the specific mechanisms responsible for TNF-α promoting cancer cell growth and invasion are largely unknown." (PMID 24676340, 2014). "Therefore, it is reasonable to hypothesize that high circulating levels of TNF-RII may attenuate the proinflammatory effects of TNF-α in patients with cancer as part of an overall state of immune tolerance." (PMID 24457057, 2014). "For instance, inducing cancer cell death by extrinsic apoptotic stimuli (such as TNF or TRAIL) might lead to the selection of cancer cells with increased NLRX1 expression that in turn would be highly susceptible to nutrient withdrawal or intrinsic stresses, such as ER stress." (PMID 24867956, 2014). "In addition, the higher ratios of IFNα2 to Th2 cytokines, including IFNα2/IL4, IFNα2/IL10, IFNα2/CCL2, IFNα2/CCL7, IFNα2/CCL11, and IFNα2/TNFα, were associated with increased odds of ER negative vs. ER positive cancer." (PMID 24473087, 2014). "Our study provided nationwide-based evidence that starting TNF-α antagonists does not increase, but rather decreases, the risk of cancer for RA patients, in comparison with those taking nbDMARDs alone, with a reduction in 7-year cumulative incidence from 5.22% to 3.84%." (PMID 25267341, 2014). "In addition, a previous study has shown that drugs targeting TNF-α may be useful for the treatment of cancers." (PMID 25202430, 2014).
cancer (continued). "Therefore, inflammation mediated by TNF-α or Wnt proteins may influence cancer progression though alterations of mitochondrial metabolism." (PMID 25019059, 2014). "Thus, neutralizing TNFα with antagonists already approved for human use offers a promising approach to abrogate IL-12 side effects during the use of this cytokine for the treatment of cancer." (PMID 24587231, 2014). "Thus, we predict that inhibition of JNK signaling might provide improved anti-cancer therapy when combined with NF-κB inhibition, potentially synergistically killing cancer cells while protecting normal tissue cells from TNF-induced damage." (PMID 25526629, 2014). "On the other hand, HOTAIR suppression sensitized cancer cells to tumor necrosis factor α (TNF-α), induced apoptosis, and rendered the cells more sensitive to the chemotherapeutic agents cisplatin and doxorubicin, indicating that HOTAIR could be a target for therapy." (PMID 25334066, 2014). "On the contrary, the most recent systemic review and meta-analysis from 63 RCTs that included 29,423 patients revealed no statistically significant increased risk of any type of cancer with use of TNF antagonists plus nbDMARDs, in comparison with use of nbDMARDs alone." (PMID 25267341, 2014). "Therefore, TNF-α expression levels may influence HPV infection and subsequent HPV-associated cancer development." (PMID 23870134, 2013). "Thus, TNFα-induced MMP-9 expression via NF-κB is important for cancer growth and metastasis." (PMID 23997800, 2013). "Finally, a recent research study reported that TNF-α resistance promotes drug resistance in malignant tumors posing an interesting hypothesis for analysis in eye research." (PMID 23587252, 2013). "Thus TGF-β and TNF-α might cooperatively alter the extracellular milieu surrounding cancer cells structurally as well as functionally." (PMID 23437179, 2013). "In addition, TNF is closely related to cancer progression and the patients' quality of life." (PMID 23864892, 2013). "It was indicated that NF-B activation plays cytoprotective role in TNF-α induced hepatotoxicity; however, the activation of NF-κB may as well promote the survival of transformed hepatocytes, thus supporting malignancy and progression in cancer." (PMID 23577221, 2013). "Clinically, the combined treatment of NF-κB inhibitor with TNF-α or with chemotherapeutic agents containing NF-κB-activated effect may offer a new strategy for the treatment of a variety of human cancers that are resistant to TNF-α or chemotherapy treatment alone." (PMID 23573150, 2013). "Although TNF-α exhibits suppressive effect in various types of cancer cells, the emerging evidences suggest that TNF-α would activate NF-κB signaling, in turn to initiate the NF-κB targeted genes expression which may potentiate the cell proliferation, invasion, and angiogenesis." (PMID 23573150, 2013). "However, the treatment of Ssd could effectively suppress the TNF-α-mediated expression of these NF-κB targeted genes in both HeLa and HepG2 cancer cells." (PMID 23573150, 2013). "However, the function of Ssd on TNF-α-induced apoptosis in cancer cells is not fully understood." (PMID 23573150, 2013). "Apart from studying the suppression effect of Ssd on TNF-NF-κB-related anti-apoptotic genes expression, it is interesting to know whether Ssd alone would activate apoptotic mediators, leading to apoptosis in cancer cells." (PMID 23573150, 2013). "However, it is still unknown whether the Rb pathway is involved in cancer-related skeletal muscle degeneration mediated by TNF-α." (PMID 24302570, 2013). "The presence of inflammatory infiltrate in cases of OED favors the transformation and invasion process when stromal TNF-α and NF-κB are overexpressed, as NF-κB activated by TNF-α during inflammation predisposes the lesion to transformation, functioning as a link between inflammation and cancer." (PMID 23833665, 2013).